KRT8P11 (keratin 8 pseudogene 11)
Synonyms: RP11-13B9.3; KRT8L1
Gene: Processed pseudogene on chromosome 9 (99,305,176 to 99,306,611, forward strand). Ensembl gene ENSG00000255815.
Diseases named in the same sentence as KRT8P11 in open-access papers:
KRT8P11 is named in the same sentence as 1 disease in open-access papers, as found by Europe PMC text mining. Sharing a sentence is not in itself a finding about the gene and the disease.
carcinoma (1 paper, 2023). A malignant tumor arising from epithelial cells.